AFP (alpha fetoprotein)
Diseases named in the same sentence as AFP in open-access papers (continued):
Sharing a sentence is not in itself a finding about the gene and the disease.
tumor (continued). "Many studies have reported the value of different tumor markers in the diagnosis of HCC, but there is currently no study using PIVKA‐II, AFP, AFP‐L3, CEA, and their combinations for the differential diagnosis of primary and metastatic HCC." (PMID 31821607, 2020). "The result showed that albumin level ≥35 g/L and AFP <100 μg/L were independent prognostic factors of HR in intermediate-stage HCC and that tumor size and tumor number were not independent prognostic factors in multivariate analysis." (PMID 33112547, 2020). "The level of the serum carbohydrate antigen-125 was elevated to 271 U/ml (normal, < 35 U/ml), while other serum tumor markers (β-HCG, AFP) were not elevated." (PMID 32483810, 2020). "Immunohistochemically, the tumor cells were positive for hepatocyte paraffin 1, AE1/AE3, and CD10 and negative for AFP, progesterone receptor, vimentin, chromogranin A, and synaptophysin." (PMID 31784920, 2019). "From the 89 patients with evaluable LDH, AFP and β-HCG, nine (10.1%) were negative for all three classical tumor markers." (PMID 31597402, 2019). "For the clinical-radiological nomogram, the alpha-fetoprotein (AFP) level, gross vascular invasion and non-smooth tumour margin were included." (PMID 31088553, 2019). "At that time, the patient’s serum AFP and PIVKA-II were within normal ranges, and enhanced CT and magnetic resonance images indicated that the tumor was still shrunken with necrotic areas, and showed no PVTT, IVCTT, or intrahepatic metastases." (PMID 31878937, 2019). "Our study therefore provides a new approach for predicting tumor size and the prognosis of HCC patients whose preoperative serum AFP concentrations are not significantly elevated." (PMID 31662990, 2019). "We subsequently performed multivariate analysis considering serum AFP and decarboxy-prothrombin (DCP) levels, tumor size, and molecular pattern; no items were revealed to be independent." (PMID 30274313, 2018). "The absence of tumor markers does not exclude malignancy, and the presence of tumor makers, particularly LDH and AFP, does not mandate malignancy." (PMID 30486309, 2018). "Although serum AFP is a well‐accepted tumor biomarker for HCC, serum levels of AFP are not elevated in 10–30% of HCC patients." (PMID 29696820, 2018). "Of the baseline tumor markers, PIVKA-II (protein induced by vitamin K absence-II) was significantly higher in the PD group than in the non-PD group (P = 0.003), unlike alpha-fetoprotein (P = 0.187)." (PMID 29558905, 2018). "High expression of ARHGAP11A was identified to be correlated with tumor size, differentiation, metastasis and TNM stage but not with other clinicopathological characteristics, such as gender, age, and AFP in patients with HCC." (PMID 30545369, 2018). "Immunohistochemical staining showed that the tumor cells were positive for CK, CK8/18, AFP, hepatocyte, GCP3, but negative for PLAP, CD10, CD30, CD34, and vimentin." (PMID 29351804, 2018). "Immunohistochemically, the tumor cells were positive for glypican-3 (GPC3) and AFP and negative for CD30." (PMID 29933751, 2018). "A serum AFP level < 1200 ng/mL after SIOPEL neoadjuvant chemotherapy and no tumor recurrence were demonstrated to be predictors of native liver survival (hazard ratio: 4.54 and 5.55; P = 0.04 and 0.02; respectively) on Cox’s proportional hazard analysis." (PMID 28851352, 2017). "Female gender (P < 0.05), vascular invasion (P < 0.001), tumours over 5 cm (P < 0.05), late TNM stage (P < 0.001) and non-surgical candidates had higher AFP levels." (PMID 29207969, 2017). "On the other hand, histological subtypes of GCT were not related to N‐glycan score, suggesting that these N‐glycans are not related to tumor‐producing proteins, such as HCG and/or AFP." (PMID 28317343, 2017). "In the univariate analysis, NLR (P = 0.017), MVI (P = 0.000), and tumor number (P = 0.000) were significant prognostic factors for DFS, whereas APRI, PLR, and AFP were not significant predictors of DFS (P > 0.05)." (PMID 29108352, 2017).
tumor (continued). "Immunohistochemical analysis performed on formalin-fixed paraffin-embedded sections showed that the tumor cells were positive for hepatocyte, CEA, and cytokine (CK) 8, but negative for AFP, CK-Pan, CK7, VM, S100, and HMB45." (PMID 29310401, 2017). "Prognostic factors such as tumor size, TNM stage, and AFP levels are not sufficient predictors of HCC recurrence after hepatectomy." (PMID 27340775, 2016). "The clinical presentation of a mediastinal tumor in a young male with an elevated serum AFP suggested NSGCT, but findings of immunohistochemistry of tumor sections were not consistent with that diagnosis." (PMID 27855672, 2016). "Consistent with the finding that SOX9 expression in the tumor was a good indicator of tumor recurrence, the serum OPN, but not AFP or PIVKA-II, level showed a significant correlation with the RFS in our analyses." (PMID 27457505, 2016). "Other prognostic factors include nonpulmonary visceral metastases and presence of high tumour markers (beta-HCG > 50000, AFP > 10000, and LDH > 10x upper limit of normal)." (PMID 27807495, 2016). "No obvious correlations with gender, tumor family history, HBsAg, median size, number of tumors, drinking, BCLC stage, recurrence, or serum AFP level were observed (all P > 0.05)." (PMID 28002346, 2016). "Multivariate analysis showed that the multiple tumors, absence of tumor capsule, PVTT, preoperative AFP positivity, and tumor diameter>5cm were the independent factors of postoperative tumor recurrence." (PMID 27182739, 2016). "Serum alpha-fetoprotein (AFP), the most widely used, has suboptimal performance with less than a fifth of early stage tumours presenting with elevated levels, and is therefore not currently recommended in American or European guidelines." (PMID 27219517, 2016). "Standard serum tumor marker carcinogenic antigen (CEA) and CA19-9 were found normal, but AFP was elevated (90.1 ng/mL) according to a cutoff of 20 ng/mL." (PMID 26976278, 2016). "The tumor size, TNM stage, Alpha-fetoprotein (AFP) level, the presence or absence of hepatitis B surface antigen (HbsAg), and differentiation degree were related to FOXO6 expression level (all P <0.05)." (PMID 27227932, 2016). "Immunohistochemically, the tumor was positive for cytokeratin (CK) 7 and CK20 (focal) and negative for placental alkaline phosphatase (PLAP), AFP, β-hCG, calretinin, and inhibin, with a Ki67/MIB1 proliferation index of 15%." (PMID 26066034, 2015). "Laboratory parameters were all normal and the tumor markers such as β-HCG, AFP, CEA, serum catecholamines were negative." (PMID 26150876, 2015). "While a previous study assessed changes in tumor marker levels at the completion of two cycles of HAIC, no clinical studies have examined AFP and DCP responses at the mid-cycle of HAIC." (PMID 25992784, 2015). "No abnormality was found in other tumor markers, including CEA (0/4), AFP (0/6), CA199 (0/4), CA242 (0/2), CA153 (0/2), and CA724 (0/1)." (PMID 25886261, 2015). "The cells of the tumor in the present study were positive for C-KIT, EpCAM and E-cadherin, but negative for other known HPC markers including AFP, K19, CD34, CD56, CD133 and albumin." (PMID 25202388, 2014). "Postoperative immunostaining of the liver tumour established the diagnosis of malignant melanoma; the tumour was focally strong-positive for HMB45 and diffuse-positive for S100, with no staining of cytokeratin (CK) and AFP." (PMID 25430016, 2014). "The immunohistochemical staining in these tumor cells was positive for CgA and Syn and negative for CEA, HPC and AFP." (PMID 24944650, 2014). "Distinguishing from a few tumor specific biomarkers (PSA, AFP, HCG etc), thymidine kinase 1 (TK1, ATP; thymidine 5′-phosphotransferase; EC.2.7.1.21) is one of the non-specific tumor markers that can be measured in continuously dividing cells." (PMID 24621590, 2014).
tumor (continued). "Cytological and pathological examination of tissue samples revealed the absence of malign cells, and this finding was also supported by the low levels of serum tumor markers (Ca-125, Ca 15-3, Ca 19-9, CEA and AFP) (data not shown)." (PMID 24804262, 2014). "Her beta hCG level was negative, and Ca-125 and other tumor markers Ca19-9, Ca15-3, CEA, and alpha-fetoprotein (AFP) were within normal limits." (PMID 23533429, 2013). "Tumor cells were immunoreactive for Hepatocyte, CK19, CEA, CA19-9 and MOC31, but negative for AFP and HM47/A9." (PMID 23599762, 2013). "AFP-level ≤100 IU/ml, number of tumor nodules ≤3 and negative pretransplant PET scans were predictive for tumor response to IBT in univariate analysis." (PMID 23349774, 2013). "Serum tumor markers human chorionic gonadotrophin (HCG beta subunit), alpha fetoprotein (AFP), and lactate dehydrogenase (LDH) were negative." (PMID 24171129, 2013). "An initial laboratory investigation returned results that were within normal ranges, while the tumor markers CEA, AFP, and CA19-9 were not elevated." (PMID 24138700, 2013). "Physical examination showed a palpable mass in the right upper abdomen, but initial laboratory results were within normal ranges; tumor markers (CEA, AFP, and CA19-9) were negative." (PMID 24138700, 2013). "In contrast to AFP, the activity levels of AFU were not correlated with tumor magnitude and AFU was of value in the diagnosis of HCC patients with negative or low serum levels of AFP, particularly for small HCC (<5 cm)." (PMID 23251247, 2013). "The representative tumor markers for HCC, AFP, and PIVKA-II are not satisfactory in terms of sensitivity and specificity in the early diagnosis of HCC." (PMID 22957256, 2012). "Immunohistochemically, the tumor cells showed positive for vimentin, while stains for CK, EMA, Calponin, CD34, AFP, hepatocyte and S-100 were all negative." (PMID 22221822, 2012). "Significant differences were found for high HIF-1α expression in relation to tumor size (P = 0.007) and HCC with extrahepatic metastasis (P < 0.001), but not in relation to patients’ gender, age, or AFP level (P > 0.05)." (PMID 22224081, 2011). "Immunohistochemically, the tumor cells were positive for GPC3, AFP, hepatocyte antigen, HepPar1, and CK18, but negative for CK7, CK20, PLAP, PSA, CA125, EMA, CD117, and CEA." (PMID 21443783, 2011). "Regarding tumor markers, carbohydrate antigen 19-9, carcinoembryonic antigen (CEA) and alpha fetoprotein (AFP) were all negative." (PMID 19889235, 2009). "Inmunohistoquemical analysis of the resected tumor was negative for CK7, CD 20, and cromogranine, while positive for CEA and AFP." (PMID 19674468, 2009). "Absence of serum tumor markers like B-HCG, CEA, alpha-fetoprotein and LDH help to exclude malignant lesion." (PMID 21151545, 2009). "Specific expression of CT antigens was observed in AFP-negative HCC, suggesting the application of their mRNA as tumor markers to detect circulating HCC cells, as adjuvant diagnostic tool, and as indicators of recurrence and prognosis." (PMID 17244360, 2007). "Immunohistochemical analysis disclosed positive staining to AE1/AE3, CK20, CK5/6, P40, c-kit and NCAM, and negative staining to CK-7, CK-8, AFP, GATA3, PSA, synaptophysin, and chromogranin A. Thus, the tumor of epithelial cell origin was confirmed through AE1/AE3 positive staining." (PMID 41515615, 2026). "Serum tumor markers in PHO, such as CEA, CA125, CA199 and AFP, may present as either normal or high, exhibiting a lack of specificity." (PMID 41479782, 2025). "Additionally, serum tumor markers—CEA, CA 15.3, CA 125, CA 19-9, and AFP—were all within normal limits, providing no immediate oncological concern." (PMID 40364141, 2025). "Not all of the tumor markers must be elevated, and our patient had a normal b-HCG but elevated AFP." (PMID 40686768, 2025). "Inhibin levels are normal, and tumor markers (CA199, CA125, CA153, AFP, CEA) are negative." (PMID 41584573, 2025).
tumor (continued). "Additionally, IGF-1 levels did not significantly correlate with liver volume, tumour volume, age, BMI, INR, ALT, or AFP, suggesting that IGF-1 does not directly reflect these HCC characteristics or patient status." (PMID 39624154, 2025). "Therefore, when both AFP and CA19−9 are elevated simultaneously, or when the elevation of tumor markers does not align with imaging findings, it suggests the possible existence of this specific tumor type, namely cHCC-CC." (PMID 40824933, 2025). "However, thickness of resection margin and AFP were correlated with DFS rather than OS, while PS score, maximal tumor size and ES classification were correlated with OS rather than DFS." (PMID 41180318, 2025). "Following successful downstaging, that is no extrahepatic disease, an AFP cutoff, and PET non-avid tumor, and response to downstaging therapy to guarantee acceptable tumor biology, patients with proven HCC with macrovascular invasion may be eligible for LDLT." (PMID 40218170, 2025). "This clinical case failed to evaluate the tumor markers characteristic of GCTs, such as human chorionic gonadotropin (HCG) and alpha‐fetoprotein (AFP), which could have assisted in differentiating the diagnosis preoperatively." (PMID 39359021, 2025). "After tumor recurrence, we administered standardized chemotherapy, and currently, the patient’s testosterone and tumor markers (such as CA125, human epididymis protein 4, CA153, CA199, CEA, AFP) are all normal, with imaging examinations also showing no tumor recurrence." (PMID 40901169, 2025). "Renal, liver, and electrolyte profiles were within normal limits, urine protein was negative, and tumor markers (cancer antigen 125 (CA-125), cancer antigen 19-9 (CA 19-9), carcinoembryonic antigen (CEA), alpha-fetoprotein (AFP)) were within the expected range for pregnancy." (PMID 41552142, 2025). "Conversely, early changes in AFP and DCP did not clearly reflect alterations in tumor size." (PMID 40940925, 2025). "Tumor markers, including CA 19-9, CEA, and AFP, were negative." (PMID 41250722, 2025). "PIVKA-II showed significant correlations with tumor size (p < 0.0001), platelet counts (p < 0.001), fibrinogen levels (p < 0.05), and values of TAT, D-dimer, and FDP (all p < 0.0001), but not with PT or AFP." (PMID 40332214, 2025). "Furthermore, there are no highly specific tumor markers currently available for PHA, and the levels of tumor markers, such as AFP, CA19-9, CA125, and CEA, are within the normal range in almost all patients." (PMID 41367857, 2025). "Examples of randomized trials show both an extension of the average survival time of patients after using OCT and a decrease in AFP concentration, as well as a lack of impact of this SSA on life extension, tumor regression or changes in AFP concentration in advanced HCC." (PMID 38540191, 2024). "Interestingly, patients with AFP < 20 ng/mL and DCP < 40 mAU/mL at baseline showed almost no change in either of the tumor markers after 4 weeks despite PD." (PMID 39321197, 2024). "In addition, subgroup studies revealed the predictive significance of fibrinogen in patients with HCC who had a single tumor and BCLC 0-A stage, as well as in patients with or without cirrhosis or high AFP levels." (PMID 39859975, 2024). "Whether DCP is superior to AFP or not is still controversial, and measurement of both postoperative AFP or DCP has been reported as a useful predictor of survival and tumor recurrence." (PMID 36832184, 2023). "In summary, we can obtain preoperative information indicating DPHCC through multimodal MRI imaging performance (including no tumour capsule, persistent enhancement pattern, and target sign on DWI) and clinical laboratory tests (including serum AFP > 20 μg/L and HBV infection prevalence)." (PMID 37578576, 2023).
tumor (continued). "AFP levels, on the other hand, had significant relationships in comparison between the presence or absence of histological HCC, in correlation between total tumor diameter, and in the ROC analysis for the diagnosis of HCC including occult HCC." (PMID 37910585, 2023). "Serum tumor markers, including TG, CA-125, CA19-9, CEA, AFP, and HE-4 were all negative." (PMID 37174972, 2023). "However, increased tumor marker levels (b-HCG, AFP, and LDH) are not accurate indicators of spermatogenesis impairment." (PMID 37512038, 2023). "With respect to tumor markers, the AFP and DCP concentrations were significantly higher in patients with non-B non-C-HCC than in patients with HBV-HCC and HCV-HCC, and the tumor size was greater in patients with non-B non-C-HCC than in patients with HBV-HCC and HCV-HCC." (PMID 37291491, 2023). "Interestingly, the AFP-immunized tumors demonstrated abundant CD8+ T cell infiltration, suggesting that they were not functional against tumor lesions." (PMID 37040183, 2023). "If the serum AFP level fails to decrease after LRT, it might be due to technical or anatomic issues, aggressive tumor biology, or undetected tumors present in other parts of the liver or outside the liver." (PMID 36900345, 2023). "Anatomical tumor recurrence between the lungs, liver, lymph nodes, bones, and brain revealed significant differential expression for CCM1, PAQR9, and PGRMC1, along with AFP, in HCC patients, while no significance was observed for CCA patients." (PMID 36980321, 2023). "However, since the correlation between AFP, GPC3, MDK, DKK1 and FNDC4 is not high, the sensitivity of FNDC4 as a tumor marker still needs further study." (PMID 38021165, 2023). "The determinants of poor prognosis were identified as non-pulmonary visceral metastases, amplification of the serum tumour markers HCG and AFP, and primary mediastinal nonseminoma and patients have been stratified into good, intermediate and poor risk categories." (PMID 38067334, 2023). "Finally, due to the limitations of the database, tumor markers such as CEA and AFP were not included in MTC patients." (PMID 38186857, 2023). "However, in contrast to AFP and fucosylated kininogen, the level of PEG-IgG was not reduced in patients who had undergone a resection, suggesting that this biomarker is not coming from the tumor itself (as are the other biomarkers) but may be associated with liver stromal factors." (PMID 36497452, 2022). "As AFP-negative HCC could be early-stage and show small tumours, imaging may not be able to provide sufficient sensitivity or specificity." (PMID 35264787, 2022). "With the predictive role of AFP and DCP being elucidated, these two tumor markers may not only contribute to the diagnosis of HCC but also help to select appropriate remedies for HCC patients." (PMID 36483039, 2022). "A major outstanding question in the 2015 consensus document for CNS GCT management was the utility and interpretation of the tumor markers human chorionic gonadotropin (HCG) and alpha fetoprotein (AFP) in the diagnosis of malignant non-germinomatous GCTs (hereafter NGGCTs) prior to treatment." (PMID 35205726, 2022). "The tumor cells were immunohistochemically positive using a pan-cytokeratin cocktail (AE1/3) as well as Ber-EP4 and CK7 positive, whereas CK20, CDX2, HMB45, Hepar-1, LCA, and AFP immunostains were negative." (PMID 36761421, 2022). "However, the results showed that three serum-exosome-derived miRNAs were not significantly correlated with tumor size, tumor number, macrovascular invasion, T-stage, AJCC-stage, and the AFP value of HCC." (PMID 36612201, 2022). "However, time to development of HCC in human patients off NTBC is certainly modeled, and the absence of fibrosis, elevated AFP, or concerning hepatic gene expression changes after over 6 months off NTBC are protective against future tumor development." (PMID 36008405, 2022).